VHL (von Hippel-Lindau tumor suppressor)
Diseases named in the same sentence as VHL in open-access papers (continued):
Sharing a sentence is not in itself a finding about the gene and the disease.
tumor (continued). "Based on genetic studies of patient material, the genetic inactivation of VHL often precedes the diagnosis of ccRCC by decades, and tumor formation is predicted to be an indolent process." (PMID 36077607, 2022). "Studies have found that increasing the expression of the VHL gene in tumor cells can effectively inhibit the proliferation of tumor cells and increase the sensitivity of tumor cells to radio chemotherapy." (PMID 35035522, 2022). "Analysing the relative CNV results, we found double doses of VHL in two, and half gene doses in four ccRCC samples out of the 30 tumour samples tested (column 3)." (PMID 35586183, 2022). "The recent phase 2 trials show a high rate of tumor stabilization with belzutifan in heavily treated patients (66% with ≥ 4 VHL procedures ≥ 4) who often face a challenging operation and/or loss of kidney function." (PMID 36310638, 2022). "VHL-related tumours such as PPGL and ccRCC show low mitochondrial content, implicating that lack of mitochondrial content is related to malignancies of tumorigenesis in the VHL syndrome." (PMID 35760869, 2022). "Several previous studies have identified miR-92a as being implicated in dysregulation and suppression of tumour suppressors, including PTEN and PHLPP2 in MCL models and VHL in CLL B-cells." (PMID 34899857, 2021). "VHL is a tumor suppressor gene that regulates cell division, cell death, cell differentiation, and response to cell stress, and it is compatible with Knudson’s two-hit theory of cancer causation." (PMID 34575959, 2021). "The abundance of independent pathologic events in VHL kidneys confirms developmental mechanisms to precede tumor initiation." (PMID 34589381, 2021). "It presents a new instrument and factor for targeting tumor-related pathologies with p-VHL/HIF altered function resulting in transcriptional, growth factors overexpression, and cancer immunity changes." (PMID 34563045, 2021). "This tumor is characterized by a high CD8+ T cell infiltration and loss of the tumor suppressor von Hippel-Lindau (VHL), which promotes HIF stabilization leading to activation of several oxygen-independent hypoxic transcriptional programs." (PMID 34025660, 2021). "VHL tumor suppressor gene inactivated in almost 80% of human ccRCCs, which leads to HIF-α protein stabilization and constitutive HIF activation." (PMID 34135317, 2021). "miR-155 has been reported to promote tumor growth by reducing VHL mRNA and HIF1 activity during prolonged hypoxia." (PMID 33809516, 2021). "The VHL gene is a tumor suppressor gene, with affected individuals inheriting a single mutated copy of the gene and a normal wild-type allele from the unaffected parent." (PMID 33670168, 2021). "In P4-pBIG2i-hIGFBP3 cells, HO-1 and VHL were highly expressed at 15 d when the tumor was the smallest and then subsided at 28 d when the tumor started to grow again." (PMID 34824343, 2021). "This implies that these alterations would have been missed if the other tumour piece was analysed alone, with the consequence that these tumours would have been considered as VHL wild-type ccRCC." (PMID 33946379, 2021). "In the light of these and previous findings, we propose an age-stratified protocol for surveillance of VHL-related tumours in individuals with apparently isolated haemangioblastoma." (PMID 34573396, 2021). "Patients with VHL develop diverse neoplasms that include hemangioblastoma of the central nervous system, retinal angiomas, renal cell carcinomas, and pheochromocytomas." (PMID 34680266, 2021). "VHL inactivation alone is insufficient for RCC tumorigenesis, and several gene mutations contribute to tumor heterogeneity that characterizes RCC." (PMID 33968762, 2021). "Both isoforms appear to retain tumor suppressor activity, and for simplicity, the term “VHL” is used when referring to both isoforms generically." (PMID 34586601, 2021).
tumor (continued). "The von Hippel–Lindau (VHL) tumor suppressor is a multisubunit Cullin RING E3 ligase (CRL2VHL)—composed of Cullin2 as the central scaffold subunit, Rbx1 as RING subunit, ElonginB and ElonginC as adaptor subunits, and VHL as substrate recognition subunit." (PMID 34174286, 2021). "Overall, the frequency distribution of somatic mutations detected in our cohort is comparable to large-scale studies of primary tumours with VHL (40.5%), PBRM1 (40.5%), and KDM5C (32.9%) being the most frequently mutated genes in our cohort." (PMID 34944839, 2021). "It has been demonstrated in RCC that the loss of VHL gene function leads to the accumulation of E2F1, which promotes cell senescence and thus inhibits tumor progression." (PMID 34499617, 2021). "The defining genetic feature of the vast majority of clear cell renal cell carcinomas (ccRCC) is biallelic inactivation of the von Hippel–Lindau (VHL) tumor suppressor gene." (PMID 34638286, 2021). "Consistent with previous reports, the classical driver mutations associated with ccRCC, including alterations in VHL, PBRM1, BAP1, and SETD2, were identified in tumor samples." (PMID 33806963, 2021). "Receptors of platelet derived growth factor (PDGF), namely PDGFR-α and -β, which transduce signals promoting angiogenesis and tumor cell proliferation, are elevated in VHL and sporadic pNET within both the tumor cells and the surrounding stroma." (PMID 34680266, 2021). "TKI inhibits the process in which mutations of the VHL gene induces HIF to accelerate VEGF for neovasculation and tumor development." (PMID 33923219, 2021). "It is all known that VHL play a critical tumor suppressor role in ccRCC, and VHL gene inactivation is by far the most common carcinogenic driving event in ccRCC." (PMID 33854630, 2021). "As a tumor suppressor, von Hippel–Lindau tumor suppressor (VHL) protein participates in mediating the ubiquitination and proteasome degradation of hypoxia inducible factor-1α (HIF-1α), inhibiting the development of HCC." (PMID 33869059, 2021). "The expression and content of VHL depended on the stage of the disease (criterion T) and the extent of the tumor process in ccRCC." (PMID 34563045, 2021). "On the other hand, CRL5–WSB1 has been shown to promote tumor metastasis and promote cell cycle via degrading tumor suppressors VHL, RhoGDI2, ATM, etc.." (PMID 34164402, 2021). "VHL inactivation leads to the constitutive stabilization of HIFs and to the increased expression of target genes involved in the unfavorable tumor microenvironment." (PMID 34359798, 2021). "As is known, the short arm of chromosome 3 is the most important region contributing to the pathogenesis of RCC, for the reason that several tumor suppressor genes, like VHL, SETD2, and PBRM1, are identified within this region." (PMID 34218253, 2021). "The inactivation of the von Hippel-Lindau (VHL) tumor suppressor gene leads to increased activity of the hypoxia-induced factor (HIF) in the tumor cell and eventually to the overexpression of platelet-derived growth factor and VEGF." (PMID 33669950, 2021). "Compared to ABT263, 753b is less toxic to platelets because platelets express lower levels of VHL than tumor cells, shown by us previously for DT22162." (PMID 34824248, 2021). "In the second patient, we verified a combination of VHL and PTEN mutations in the primary tumor and both metastases." (PMID 34885018, 2021). "It is important to highlight that HIF-1α can also be subjected to negative regulation by tumour suppressors such as Von Hippel-Lindau (VHL) and (PTEN)." (PMID 34798868, 2021). "At the retinal level, VHL protein is able to regulate tumor growth, angiogenic factors, and neuroinflammation, probably stimulating retinal glial cells." (PMID 35008334, 2021). "One unresolved question concerns the relationship between the expression of these genes and the type of VHL alterations found in the tumor samples." (PMID 34359798, 2021).
tumor (continued). "The von Hippel-Lindau (VHL) gene is a tumour suppressor gene that regulates activity of hypoxia-induced factor (HIF) and expression of vascular endothelial growth factor (VEGF) and platelet-derived growth factor (PDGF)." (PMID 34527581, 2021). "For instance, multiple PBRM1-driven and VHL monodriver subtypes predominately progress to a solitary metastatic site, whereas ccRCC tumours with multiple clonal drivers, BAP1-driven, and VHL wildtype subtypes show rapid progression to multiple sites." (PMID 34944839, 2021). "Growth rates help guide the frequency of active surveillance of renal lesions, especially in VHL patients who undergo imaging every 12–36 months based on their established tumor growth and current size." (PMID 33670168, 2021). "In a recent retrospective report including 17 VHL-related panNENs, seven patients with tumor size <3 cm were treated conservatively, with all but one displaying stable disease at a 2 year median follow-up." (PMID 34885063, 2021). "Cell lines and primary normal or tumor cells with an active VHL (A, C2, 15S, TF) have undetectable or low levels of Plk1 as compared to VHL-i cell lines and primary cells (R4, R10, 786, 498, MM, CC)." (PMID 33547392, 2021). "An emerging role of VHL biology is its effects on the tumor microenvironment, and there is evidence that the VHL pathway targets the hypoxia-inducible factors (HIFs) family of transcription factors." (PMID 34359798, 2021). "HIF-1α is marked for degradation by a cullin–RING E3 ligase complex in which the von Hippel-Lindau (VHL) tumor suppressor protein acts as the substrate recognition element." (PMID 33682442, 2021). "There was a decrease in the VHL expression in the metastases by 1.89 times and its content by 3.17 times compared with the primary tumor." (PMID 34563045, 2021). "Von Hippel Lindau (VHL), a tumor suppressor, targets HIF1α/2α by ubiquitination involving E3 ligase to proteasomal degradation." (PMID 35145899, 2021). "The uncontrolled overexpression of HIF’s target genes in VHL (−/−) cells ultimately leads to rapid proliferation and angiogenesis, promoting tumor formation in VHL patients." (PMID 34571962, 2021). "Since a majority of the DASEs never develop into frank tumors, two-hit inactivation of the VHL gene is necessary but insufficient for tumor development." (PMID 34589381, 2021). "Primary ccRCC tumours are characterized by genomic aberrations in the tumour suppressor gene VHL as well as variations in other driver genes such as BAP1, PBRM1, and SETD2." (PMID 34944839, 2021). "The lower VHL expression in cancers is a sign of the aggressive tumor’s behavior and neoangiogenesis initiation." (PMID 34319022, 2021). "VHL is a tumor suppressor gene and plays a key role in cellular oxygen sensing and the tumorigenesis of ccRCC." (PMID 34568025, 2021). "The expression of VEGF and PDGF is significantly upregulated in RCC as a result of VHL inactivation, which, on the one hand, accelerates growth of tumor, on the other hand, is also its weakness." (PMID 33510766, 2020). "We also found LOH at the CDKN2A gene locus and abundant Cyclin D1 expression in the tumor in this VHL patient." (PMID 31673890, 2020). "VHL, a tumor suppressor, functions as part of a ubiquitin ligase complex that recognizes HIF-1α as a substrate and is part of the oxygen-sensing mechanism of the cell." (PMID 33013381, 2020). "We were also able to induce the expression of the E74-like factor 5 (ELF5), a tumor suppressor in RCC, in the 786-0, VHL deficient, RCC cell line under hyperosmotic cell culture conditions." (PMID 32059438, 2020). "It has been shown that VHL expression is negatively correlated with tumor malignancy through promoting immune responses and in patients, mutated VHL ligase proteins were found to show more natural killer cell toxicity." (PMID 32882786, 2020). "The Von Hippel-Lindau (VHL) tumor suppressor is lost on the short arm of chromosome 3 in the majority of ccRCC (80%)." (PMID 33643028, 2020).
tumor (continued). "In 2013, a PROTAC based on a peptide ligand for VHL was first demonstrated to inhibit tumor growth in murine models." (PMID 32718354, 2020). "An additional novel group, in which the primary cilium is re-expressed or maintained, lacked VDAC1-ΔC yet maintained glycolysis, a signature of epithelial-mesenchymal transition (EMT) and more aggressive tumor progression, but was independent to VHL." (PMID 32194829, 2020). "Despite the limited group size and the lack of a priori strategy, these data are not conclusive but consistent with our cell culture and in vivo studies and thus provide further rationale for using propranolol in the treatment of VHL-related neoplasms." (PMID 32854260, 2020). "The von Hippel Lindau (VHL) is a typical tumor suppressor gene, and most RCC have VHL gene abnormalities including VHL gene mutations, methylation and loss of heterozygosity." (PMID 33256799, 2020). "VHL is a tumor suppressor that plays a pivotal role in the development of ccRCC and gene alterations can be found in up to 90% of ccRCC cases." (PMID 32059438, 2020). "It is well known that loss of VHL leads to induction of the hypoxia inducible factor (HIF), which in turn promotes tumor growth." (PMID 33643028, 2020). "The combinations (SF + MU: 5/0.1, 5/0.2) were equally effective in both VHL+ and VHL− RCC cell lines; VHL is a tumor suppressor that is frequently mutated or deleted in RCC36." (PMID 32427869, 2020). "Univariate and multivariate Cox regression analysis of age-related VHL tumor risks of NoF1 vs. N2TR." (PMID 33362845, 2020). "Some compounds targeting the VHL/HIF axis can inhibit tumor growth in both animal models and clinical trials." (PMID 33329393, 2020). "Since VHL lacks an effective treatment, new drugs able to prevent repeated surgeries and to delay tumor development, including ccRCC, are in demand." (PMID 32854260, 2020). "As previous studies reported that VHL mutant tumor cells have stronger heterogeneity or tumor neoantigen levels, we performed further investigation on the hierarchical analysis." (PMID 33372609, 2020). "Of genes previously reported as commonly mutated in PNETs, only PDGFRA and MTOR were found to be mutated in a few tumor samples, and other genes, including ATM, ATRX, TSC2, DAXX, VHL, and MEN1, were mutated only in individual samples." (PMID 32586046, 2020). "The larger tumor harbored a frameshift deletion in VHL (NM_000551: c.408delT: p.Phe136Leufs*23: rs397516442) in 49% of reads but no somatic mutations in VHL were detected in the smaller tumor." (PMID 31943436, 2020). "The angiogenic program in ccRCC is switched on deficiency of VHL protein, resulting in excess of HIF-1 proteins, which recruit vascular cells for the tumor vessel plexus formation." (PMID 32668608, 2020). "In VHL syndrome and sporadic RCCs, germline and somatic mutations in the VHL gene lead to upregulation of proangiogenic HIF through the VHL tumour suppressor pathway." (PMID 33167498, 2020). "A direct interaction with the von-Hippel-Lindau tumor suppressor protein (pVHL), a known tumor suppressor, has been reported." (PMID 32294979, 2020). "In the precise case of ccRCC (clear cell renal cell carcinoma), up to 95% of the tumor genomes are constitutionally VHL gene muted or deleted, thus leading to constitutive activation of HIF1 and CAIX upregulation, even in normoxic conditions." (PMID 32998233, 2020). "pVHL is also mutated in a majority of cases of the sporadic form of ccRCC, indicating that VHL is a major tumor driver in ccRCC." (PMID 32284789, 2020). "Univariate and multivariate Cox regression analysis of age-related VHL tumor risks of NoF1 vs. NoF2." (PMID 33362845, 2020).
tumor (continued). "Up to now, two major types of factors have been found to be involved in RCC metastasis: one is tumour angiogenesis factors that can promote metastasis, such as MMPs and CD44, and the other is tumour suppressors, such as VHL and PTEN." (PMID 32209138, 2020). "The tumor cells, used in this study are genetically different (VHL/HIF2α) and expressed different integrins and ECM receptors." (PMID 32411604, 2020). "Due to the fast growth of tumor tissues, this process occurs in all solid tumors, and dysregulated VHL/HIF axis further exacerbate the development of certain tumors such as PPGLs." (PMID 33329393, 2020). "A recent study has shown that another Navitoclax derivative, namely DT2216, exerts anti‐tumour activity by targeting BCL‐ XL to the VHL E3 ligase for proteolytic degradation." (PMID 32233024, 2020). "Tumor growth was assessed by urologists and radiologists specialized in VHL, through enhanced MRI and/or ultrasound every six months." (PMID 32854260, 2020). "Does this now mean that VHL functions as a ‘tumor-promoter’ given the proliferation experimental observations in RENCA and HK-2 cell lines?" (PMID 33077781, 2020). "In glioma, the targeted inhibitory effect of increasing miR-23b on VHL unsurprisingly activates HIF-1α/VEGF signaling to promote tumor progression." (PMID 32014012, 2020). "In their 1999 hallmark paper in Nature, a critical role for the von Hippel-Lindau (VHL) tumour suppressor (pVHL) in HIF-1 regulation was identified." (PMID 32579052, 2020). "We have developed DT2216, a proteolysis targeting chimera (PROTAC) targeting Bcl-xL for degradation via Von Hippel-Lindau (VHL) E3 ligase, and shown that it has better anti-tumor activity but is less toxic to platelets compared to ABT263." (PMID 32677976, 2020). "Many tumor suppressor genes, such as VHL, members of the Wnt and TGFβ pathways and pro-apoptotic genes, have been identified to be partially or completely silenced due to hypermethylation in ccRCC24." (PMID 32929120, 2020). "VHL protein has emerged as a potent tumor suppressor governing various signaling pathways that promote oncogenic phenotypes and fitness." (PMID 32513235, 2020). "The normal function of von Hippel–Lindau (VHL) tumor suppressor can abolish the hypoxia-inducible transcription factor (HIF) and HIF acts as an important oncogene to promote renal tumor growth." (PMID 31155610, 2020). "Firstly, multiple workers have shown that VHL loss and HIF activation occur at the very earliest stages of ccRCC formation, whereas in other tumour types HIF activation only develops in late stages once the tumour has outgrown its blood supply." (PMID 31822727, 2019). "The VHL protein (pVHL) functions as a tumor suppressor and is responsible for the ubiquitination and proteasome degradation of hypoxia-inducible factors (HIFs)." (PMID 30872677, 2019). "An alternative start codon at codon 54, which harbors the next methionine, is presumed to initiate VHL translation, thus forming an alternative protein product, which is thought to possess tumor suppressor properties partially similar to wildtype VHL." (PMID 31034483, 2019). "Altogether, ICI is partially counteracting the HIF response, constitutively activated in VHL tumour cells." (PMID 31296894, 2019). "Altogether these results support a key role for RSUME on the early angiogenesis needed for tumor establishment by Type 2 VHL mutants." (PMID 30890701, 2019). "Hypoxia is one of the important characteristics of a majority of solid tumors, Moreover, the ccRCC tumors are spontaneously hypoxic, since Von Hippel-Lindau (VHL) is an important tumor suppressor that is lost in the majority of ccRCC." (PMID 30796197, 2019). "During normoxic conditions, prolyl-hydroxylases (PHDs) hydrolyze HIF-1α, which can then be recognized by the von Hippel–Lindau (VHL) tumor suppressor." (PMID 31354653, 2019). "Tumor heterogeneity and differences in growth kinetics is suggestive of a state of transient tumor dormancy in ccRCCs of VHL patients." (PMID 31661010, 2019).